EREG (epiregulin)
Diseases named in the same sentence as EREG in open-access papers (continued):
Sharing a sentence is not in itself a finding about the gene and the disease.
cholesteatoma (2 papers, 2013 to 2021). A pathologic process characterized by the proliferation of keratinizing squamous epithelium resulting in the accumulation of keratin and cells in the middle ear and/or mastoid. "The quantitative polymerase chain reaction and immunohistochemistry were performed to examine epiregulin expression and localization in cholesteatoma tissues and retroauricular skin tissues." (PMID 23826119, 2013). "The present study showed that expression of epiregulin was enhanced in the epithelial cells and subepithelial fibroblasts of cholesteatoma tissue compared with normal retroauricular skin." (PMID 23826119, 2013). "We also performed immunohistochemistry, which revealed that epiregulin staining was stronger in the epithelial cells and subepithelial fibroblasts of cholesteatoma tissue than in those cells of retroauricular skin." (PMID 23826119, 2013). "This study demonstrated the overexpression of epiregulin in epithelial cells and subepithelial fibroblasts of cholesteatoma tissue." (PMID 23826119, 2013). "Staining for epiregulin was more intense in the epithelial cells and subepithelial fibroblasts of cholesteatoma tissues than in retroauricular skin." (PMID 23826119, 2013). "Epiregulin mRNA expression was significantly elevated in cholesteatoma tissues compared with that in normal retroauricular skin." (PMID 23826119, 2013). "Thus, epiregulin is a candidate factor responsible for fibroblast overactivity that influences the epithelium in cholesteatoma." (PMID 23826119, 2013). "Also, knockdown of epiregulin mRNA in cholesteatoma fibroblasts led to greater suppression of colony formation than knockdown in skin fibroblasts." (PMID 23826119, 2013). "The expression of the growth factors KGF, EGF, EREG, IGF-2 and HGF was significantly higher in fibroblasts, particularly when derived from cholesteatoma." (PMID 33627146, 2021). "Beyond this growth factors crucial for epidermal growth and wound healing, e.g. EGF, KGF, Epiregulin, bFGF, TGF-β1 and HGF, were upregulated as well in cholesteatoma tissue." (PMID 33627146, 2021). "Furthermore, the colony-forming efficiency of PHK16-0b cells was significantly reduced after treatment with an epiregulin neutralizing antibody in co-culture with cholesteatoma fibroblasts, but not in co-culture with skin fibroblasts." (PMID 23826119, 2013). "However, there have been no reports about the role of epiregulin in cholesteatoma." (PMID 23826119, 2013).
endometrial cancer (2 papers, 2008 to 2021). Primary or metastatic malignant neoplasm involving the endometrium (mucous membrane that lines the endometrial cavity). "Our preclinical findings, however, do suggest that increased expression of EGFR ligands such as amphiregulin, TGF-α, epiregulin, or NRG1 may also be associated with sensitivity to lapatinib in endometrial cancer." (PMID 18334972, 2008).
esophageal cancer (2 papers, 2022 to 2024). A primary or metastatic malignant neoplasm involving the esophagus. "Similarly, EREG-overexpressed esophageal cancer cells demonstrated promoted migration and invasion." (PMID 38673992, 2024).
liver fibrosis (2 papers, 2020 to 2025). "We then evaluated the changes in epiregulin expression in cell models of liver fibrosis." (PMID 33520984, 2020). "It remains to be ascertained whether these epiregulin deficient mice would phenocopy the AREG–/– mice and the HB-EGF–/– mice in models of liver fibrosis." (PMID 33520984, 2020). "Previously it has been shown that amphiregulin (AR), an EGFR ligand closely related to epiregulin (EREG), is activated during HSC trans-differentiation and contributes to liver fibrosis." (PMID 33520984, 2020).
lung fibrosis (2 papers, 2019 to 2022). "In mouse models of skin and lung fibrosis, epiregulin was essential for persistence of fibrosis in both tissues, which could be abrogated by epiregulin genetic deficiency or a neutralizing antibody." (PMID 36490328, 2022). "Both Ereg Ab and TGF-βRI/Alk5 inhibitor reduced EREG expression similar to what we observed in mouse lung fibrosis, suggesting a regulatory link between EREG expression and TGFβ signaling." (PMID 36490328, 2022). "Our findings reveal epiregulin as a crucial immune signal that maintains skin and lung fibrosis in multiple diseases and represents a promising antifibrotic target." (PMID 36490328, 2022). "Altogether, these findings show that EREG inhibition attenuates skin and lung fibrosis in mice." (PMID 36490328, 2022). "Based on the efficacy of EREG inhibition to reverse skin fibrosis, we examined if EREG inhibition could also treat lung fibrosis." (PMID 36490328, 2022). "Therefore, in mice exposed to bleomycin, Ereg has defined expression patterns during both skin and lung fibrosis, rendering the model useful for understanding EREG-EGFR signaling in relation to human disease." (PMID 36490328, 2022). "We show that EREG expression is induced by type I interferon and co-expressed with alarmins S100A8 AND S100A9, which aligns our findings to previous clinical studies that associated circulating levels of type I interferon and S100A8/A9 with severity of SSc skin and lung fibrosis." (PMID 36490328, 2022). "To best interrogate the role of EREG in SSc in vivo, we required a mouse model that depends on myeloid APC and induces both skin and lung fibrosis." (PMID 36490328, 2022). "Epiregulin is an EGFR ligand produced by DC3 dendritic cells that is essential for persistence of skin and lung fibrosis." (PMID 36490328, 2022). "Our previous studies demonstrate upregulation of multiple growth factors including TGFβ, IL-6, IL-13, amphiregulin and epiregulin in distinct mesenchymal cell subsets such as fibrocytes, lung resident fibroblasts and WT1-positive myofibroblasts during TGFα-induced pulmonary fibrosis." (PMID 31156440, 2019).
Obesity (2 papers, 2012 to 2022). Accumulation of substantial excess body fat. "EREG/LepR regulated glucose uptake without changes in obesity in Lepob mice via mechanisms, including ERK activation and translocation of GLUT4 to the cell surface." (PMID 35159237, 2022).
osteosarcoma (2 papers, 2012 to 2024). A usually aggressive malignant bone-forming mesenchymal neoplasm, predominantly affecting adolescents and young adults. "Another study identified two genes not previously linked to osteosarcoma, epiregulin (EREG) and carbohydrate (N-acetylglucosamine-6-O) sulfotransferase 2 (CHST2), both predictive for survival." (PMID 22518090, 2012).
ovarian tumors (2 papers, 2023 to 2024). "The pro-angiogenic macrophage subpopulation (Mac_Angio, n = 3108) displayed high expression of genes associated with angiogenesis, such as VEGFA, VCAN, and EREG, and was found enriched in lung and ovarian tumors." (PMID 38972873, 2024). "Multicolor imaging data further confirmed the coexistence of monocyte-derived M07 EREG+ macro and RTM-derived M10 C1QA+ macro in ovarian tumors." (PMID 37488416, 2023).
pancreatic adenocarcinoma (2 papers, 2022 to 2023). "used the risk score method to identify 3 genes associated with adverse prognosis of pancreatic adenocarcinoma (PAAD), ERAP2, CKLF and EREG, and constructed a nomogram based on clinical features and risk score for individualized prognosis prediction." (PMID 35757399, 2022).
renal carcinoma (2 papers, 2022). A carcinoma arising from the epithelium of the renal parenchyma or the renal pelvis. "This indicates that MIAC directly binds to AQP2, and finally plays a role in inhibiting the occurrence and development of renal cancer by inhibiting the expression of EREG and EGFR and the activation of downstream signaling pathways." (PMID 36117171, 2022). "And mechanism studies showed that MIAC inhibits the activation of the EREG/EGFR signaling pathway by direct binding to AQP2 protein, thereby inhibiting renal cancer progression and metastasis in vitro and in vivo." (PMID 36117171, 2022). "This study revealed for the first time the tumor suppressor potential of the lncRNA-encoded micropeptide MIAC in RCC, which inhibits the activation of the EREG/EGFR signaling pathway by direct binding to AQP2 protein, thereby inhibiting renal carcinoma progression and metastasis." (PMID 36117171, 2022).
rheumatoid arthritis (2 papers, 2021). A chronic, systemic autoimmune disorder characterized by inflammation in the synovial membranes and articular surfaces. "Amphiregulin (AREG) and epiregulin (EREG) are type II cytokines linked to a wide variety of inflammatory conditions, such as rheumatoid arthritis, chronic airway disease and glomerulonephritis." (PMID 34177613, 2021). "Human data indicate that both amphiregulin and epiregulin expressions were higher in bone marrow-derived mononuclear cells of rheumatoid arthritis patients and increased expression of amphiregulin was also detected in PBMCs and synovial tissues." (PMID 34615455, 2021).
Skin rash (2 papers, 2011 to 2021). A red eruption of the skin. "TTP and OS to the ≥2nd line cetuximab-containing treatment according to KRAS, BRAF, PIK3CA mutations status, PTEN protein expression, AREG and EREG mRNA expression and grade of skin rash in the whole patient′ population." (PMID 21283802, 2011). "Multivariate analysis revealed KRAS (Hazard Ratio [HR] 4.3, p<0.0001), BRAF mutation (HR: 5.1, p<0.0001), EREG low expression (HR: 1.6, p = 0.021) and absence of severe/moderate skin rash (HR: 4.0, p<0.0001) as independent prognostic factors for decreased TTP." (PMID 21283802, 2011). "As far as TTP was concerned, the univariate analysis demonstrated significant associations with: i) KRAS mutations (p = 0.001); ii) BRAF mutations (p = 0.001); iii) AREG mRNA expression (p = 0.018); iv) EREG mRNA expression (p = 0.002) and v) the development of moderate severe skin rash (p<0.0001)." (PMID 21283802, 2011). "EGFR ligands like epiregulin (EREG), amphiregulin (AREG), and hepatocyte growth factor (HGF) were investigated as biomarkers for skin rash and found to be inversely proportional to grades of skin toxicity." (PMID 34012511, 2021).
squamous cell carcinoma (2 papers, 2017 to 2018). A carcinoma arising from squamous epithelial cells. "Expression of EREG mRNA has also been found to be higher in adenocarcinomas versus squamous cell carcinomas." (PMID 30412601, 2018).
abortion (1 paper, 2020). the ending of pregnancy by removing a fetus or embryo before it can survive outside the uterus. "In the present study, the serum level of epiregulin and poFUT1 in pregnancy women and abortion patients were examined, and the decreased levels of epiregulin and poFUT1 were associated with abortion." (PMID 31889361, 2020). "We compared the expression of epiregulin and poFUT1 in the villi of pregnant women and abortion patients." (PMID 31889361, 2020). "It was worth noting that there was a positive correlation between the epiregulin and poFUT1 expression levels in the serum of pregnant women (r = .9710) and abortion patients (r = .9237)." (PMID 31889361, 2020). "Western blot also showed that epiregulin and poFUT1 levels were higher in the pregnant women than in the abortion patients." (PMID 31889361, 2020). "Immunofluorescence staining showed that epiregulin and poFUT1 were localized in villous trophoblast cells, and both stainings were stronger in normal pregnant women than in abortion patients." (PMID 31889361, 2020). "As shown by ELISA, the levels of epiregulin, poFUT1 and uPA were decreased in the serum of abortion patients compared with pregnant women." (PMID 31889361, 2020). "Serum levels of epiregulin and poFUT1 were higher in pregnant women compared with non‐pregnant women, and their levels were significantly decreased in abortion patients compared with pregnant women." (PMID 31889361, 2020).
breast tumor (1 paper, 2015). "Based on findings in which EREG was found to be highly upregulated in MCF10DCIS cells in comparison with MCF10A cells, the studies described here focus on determining the potential contributions of EREG to early stages of breast tumor formation." (PMID 26215578, 2015). "However, the contributions of EREG to early stages of breast tumor initiation and growth have not been investigated." (PMID 26215578, 2015).
cardiac hypertrophy (1 paper, 2022). "The findings of this study suggest that EREG partially contributes to cardiac hypertrophy." (PMID 35719043, 2022).
cavernous hemangioma (1 paper, 2022). A hemangioma characterized by the presence of cavernous vascular spaces. "Among all types of cells in the cavernous hemangioma, only m1Maph highly expressed EREG, which provided a deeper understanding of the origin and functions of epiregulin in the immune responses." (PMID 35865633, 2022).
Cerebral ischemia (1 paper, 2015). Restriction of arterial blood supply to the brain associated with insufficient oxygenation to support the metabolic requirements of the tissue. "We found that the expression levels of amphiregulin and epiregulin were significantly increased under conditions of cerebral ischemia." (PMID 25675253, 2015).
colorectal tumors (1 paper, 2024). "OSBPL2 was negatively correlated with VCAN, AREG, and EREG, whereas there was a positive correlation between VCAN, AREG, and EREG in colorectal tumors." (PMID 38267463, 2024).
ductal carcinoma (1 paper, 2023). "Up-regulated EREG levels were also described in human ductal carcinoma lesions compared to normal breast epithelium, and they predicted poor prognosis." (PMID 37447165, 2023).
dysplasia (1 paper, 2009). A usually neoplastic transformation of the cell, associated with altered architectural tissue patterns. "Specifically, in dysplasia genes coding for nucleic acid metabolism or cell cycle regulation were unchanged but two EGF-ligands, namely amphi- and epiregulin were highly significantly up-regulated." (PMID 19529782, 2009).
extra-pulmonary tuberculosis (1 paper, 2019). "In summary, we suggest that EREG gene polymorphism confers susceptibility to pulmonary tuberculosis and extra-pulmonary tuberculosis." (PMID 30634928, 2019).
heart arrhythmia (1 paper, 2019). "Five genes (PRKCG, EREG, BHLHE40, KLF10, and NAMPT) targeted by AA-miRNAs may contribute to the pathogenesis of heart arrhythmia such as AF." (PMID 31607954, 2019).
Hydrocephalus (1 paper, 2016). Hydrocephalus is an active distension of the ventricular system of the brain resulting from inadequate passage of CSF from its point of production within the cerebral ventricles to its point of absorption into the systemic circulation. "Previous studies show that AREG can upregulate mucin gene expression in obstructive airway diseases, EREG modulates Toll-like receptor (TLR)-mediated immune responses, and HB-EGF overexpression promotes vascular endothelial growth factor (VEGF) signaling resulting in hydrocephalus." (PMID 27756321, 2016).
Infertility (1 paper, 2020). "Our findings are essential in that they identify early markers (poFUT1 and epiregulin) of miscarriage in serum and trophoblastic cells, which may serve as new biomarkers for clinical diagnosis and provide the foundation for strategies of infertility treatment." (PMID 31889361, 2020).
influenza infection (1 paper, 2019). "However, changes in expression of certain growth factors (including EREG and FGFs) following influenza infection may lead to complications involving airway remodeling and recruitment." (PMID 31461941, 2019).
intracranial aneurysms (1 paper, 2022). "Several of these target genes have been reported to be closely related to the formation, growth and rupture of intracranial aneurysms, including transglutaminase 2 (TGM2), epiregulin (EREG), endothelin-1 (EDN1) and alpha 1 type IV collagen (COL4A1)." (PMID 35242102, 2022).
kidney cancer (1 paper, 2022). Primary or metastatic malignant neoplasm involving the kidney. "This study found and confirmed for the first time that MIAC directly binds to AQP2 inhibiting the expression of EREG, EGFR and the activation of downstream PI3K/AKT and mTOR signaling pathways to achieve the inhibitory effect of kidney cancer growth and metastasis." (PMID 36117171, 2022).
leukemia (1 paper, 2022). A malignant (clonal) hematologic disorder, involving hematopoietic stem cells and characterized by the presence of primitive or atypical myeloid or lymphoid cells in the bone marrow and the blood. "The Re trajectory (cluster 5 towards cluster 9) is hallmarked by upregulation of numerous genes required for differentiation, leukemia progression and chemo-resistance, including RACK1, EREG and LOXL1." (PMID 35986270, 2022).
lymph node metastasis (1 paper, 2025). "Moreover, epiregulin expression is associated with lymph node metastasis and shortened survival in NSCLC, and the invasiveness of NSCLC cell lines with activating EGFR mutations can be reduced by silencing epiregulin or by using antibody treatments." (PMID 40347011, 2025).
middle ear cholesteatoma (1 paper, 2013). "We assessed the expression of epiregulin mRNA by quantitative PCR, and found that it was significantly higher in middle ear cholesteatoma tissue than in normal retroauricular skin." (PMID 23826119, 2013). "In conclusion, our present results suggest that keratinocyte hyperproliferation in middle ear cholesteatoma might be induced through overproduction of epiregulin by subepithelial fibroblasts." (PMID 23826119, 2013). "This suggested that fibroblasts might play a role in the development of hyperkeratosis during the pathogenesis of middle ear cholesteatoma through overexpression of epiregulin rather than KGF." (PMID 23826119, 2013).
Miscarriage (1 paper, 2020). A pregnancy that ends at a stage in which the fetus is incapable of surviving on its own, defined as the spontaneous loss of a fetus before the 22th week of pregnancy. "In the current study, we further found that a lower level of epiregulin was associated with miscarriage, and epiregulin facilitated the invasion and EMT in trophoblastic cells." (PMID 31889361, 2020).
polycystic ovary syndrome (1 paper, 2025). A disorder that manifests as multiple cysts on the ovaries. "Women with polycystic ovary syndrome exhibited significantly lower epiregulin levels compared to controls (p<0.001)." (PMID 40638469, 2025). "Serum epiregulin levels were analyzed in 39 women with polycystic ovary syndrome and 28 healthy controls." (PMID 40638469, 2025). "This study aimed to investigate the role of epiregulin, an EGF family member implicated in ovulation and oocyte maturation, in women with polycystic ovary syndrome." (PMID 40638469, 2025). "Demographic data, epiregulin levels, and hormonal profiles of the polycystic ovary syndrome group and the control group." (PMID 40638469, 2025). "Reduced epiregulin levels may contribute to the pathophysiology of polycystic ovary syndrome, highlighting its potential as a biomarker and therapeutic target." (PMID 40638469, 2025). "Parameters showing a significant correlation between epiregulin and polycystic ovary syndrome." (PMID 40638469, 2025).
Sciatica (1 paper, 2021). Pain in the lower back and hip radiating in the distribution of the sciatic nerve. "To facilitate the diagnosis of sciatica by clinicians using the selected DEIRGs (RLN1, EREG, FAM19A4, WFIKKN1, and CRP), we constructed a nomogram model." (PMID 34925462, 2021). "AZU1, BPI, TCF7L2, and WFIKKN1 were upregulated in sciatica patients, while ANGPTL4, CRP, EREG, FAM19A4, FGF1, LOC100129216, PLXNB1, RLN1, and RXFP2 were downregulated." (PMID 34925462, 2021).
skin tumor (1 paper, 2014). "However, inhibitors to Epidermal growth factor receptor (EGFR) and MAP kinse-ERK kinase (MEK) (a downstream molecule in the EGFR pathway) did not change the elevated level of EREG in TSC skin tumor." (PMID 24748662, 2014).